SOX2 (SRY-box transcription factor 2)
Diseases named in the same sentence as SOX2 in open-access papers (continued):
Sharing a sentence is not in itself a finding about the gene and the disease.
tumor (continued). "Next, we tested if TRIM26 and WWP2 control SOX2 protein levels in tumor cells in vivo." (PMID 34732716, 2021). "Regarding the molecular mechanisms of SOX2 in tumor invasion and metastasis, some studies have shown that SOX2 up-regulation results in increased phosphorylation of multiple pro-metastatic proteins, such as Src, FAK, and their downstream molecules, such as p130-cas." (PMID 34436030, 2021). "Insights into the mechanisms that limit growth of the tumor could help develop clinical strategies that prevent the SOX2+ SHH MB tumor-initiating cells from repopulating the tumor after completion of standard of care." (PMID 35054230, 2021). "Moreover, M-CFN effectively promoted accessibility to the ALDHA1-, SOX2- or Oct4-expressing CSC fractions in tumor." (PMID 34838042, 2021). "Overall, our findings suggest that SOX2 may be a more consistent indicator of ovarian TICs that contribute to tumor repopulation following chemotherapy." (PMID 33445692, 2021). "Further research is needed to address whether overexpression of SOX2 in HCC occurs before that of other tumor markers, in particular of AFP." (PMID 34436030, 2021). "Finally, xenograft models revealed that inhibition of SOX2 expression and autophagy restrained tumor growth and chemoresistance in vivo." (PMID 33953166, 2021). "We were interested in determining whether this difference in time to tumor-initiation within different dilution groups could be correlated with SOX2, OCT4, or NANOG expression." (PMID 33445692, 2021). "The tumor-specific SE-associated genes were enriched in important pathways, such as chordate embryonic development (RUNX2, FOXA1), regulation of cell adhesion (RUNX1, SOX2 and VEGFA), and epithelial cell differentiation (SOX9, ELF3)." (PMID 34001209, 2021). "We could also show that the well-established cancer stem cell marker SOX2 level was decreased in the residual tumours from mice treated with CBL and Rova-T, compared to controls, with the drug combination being most effective." (PMID 33257843, 2021). "Moreover, a correlation of SOX2 expression with tumor grade, invasiveness, and patients’ lower survival was found." (PMID 33804155, 2021). "It suggests that SOX2+ CSC‐like tumor cells in HNSCC might be intrinsically resistant to CD8+ T cell killing." (PMID 34258151, 2021). "Moreover, tumor-derived exosomal SOX2 overlapping transcript also play an important role in modulating the polarization of TAMs in NSCLC though regulating SOX2/miR-627-3p/Smads axis." (PMID 35047506, 2021). "In GBM patients, the IAP protein, survivin, was demonstrated to be mainly expressed in patient-derived GBM stem cells compared to differentiated cells, with a predominant localization in the core of tumor mass and associated with the expression of CD133, SOX2 and MELK." (PMID 34354950, 2021). "This might explain the role of SOX2 in tumor progression via the self-renewal and activation of reprogramming mechanisms of cancer cells." (PMID 34436030, 2021). "Moreover, the tumor tissue overexpressed SOX2, a characteristic finding of SMARCA4-deficient neoplasms." (PMID 34131151, 2021). "Importantly, we also found that SOX2, a well-known GBM cell stemness marker, is almost undetectable in the SON shRNA-expressing tumor section while control tumors showed robust SOX2 expression." (PMID 34548489, 2021). "This raises the question of whether the subset of Sox2-positive cells in the 2XSB tumor are cancer stem-like cells or simply a subpopulation with features similar to immature or dedifferentiated Schwann cells." (PMID 33707600, 2021). "IL20RA and SOX2 were increased in tumor tissues compared to normal/para-carcinoma tissues." (PMID 33456560, 2021). "Therefore, our results showing the opposite in tumor samples for SOX2 are challenging new studies to be conducted to find out more about SOX2 expression." (PMID 33471801, 2021).
tumor (continued). "Additionally, knockdown of SOX2 notably counteracted PAK2 upregulation-induced tumor-promoting effects on cell proliferation, migration, and expression of EMT-related factors." (PMID 34621737, 2021). "Additionally, SOX2 expression was found to be positively correlated with the proliferation and migration capacities of tumor cells, and its high expression is a poor prognostic marker for OC." (PMID 34621737, 2021). "Hence, CD44 provides a physical link between the extracellular matrix and transcription factors such as Oct4, Sox2, and Nanog that, in turn, regulate tumour cell function." (PMID 34831291, 2021). "To assess whether the in vitro stemness enrichment was maintained in vivo after tumor formation, we evaluated the harvested tumors for SOX2 protein expression using IHC." (PMID 33372065, 2021). "Second, this SOX2-inducible model system could be used as a platform to screen a library of drugs, particularly FDA-approved drugs, for their ability to eradicate SOX2 growth-arrested tumor cells in vivo." (PMID 35054230, 2021). "In pancreatic cancer, hCAP-18/LL-37 was strongly expressed by macrophages in response to tumor-derived Activin A, and increased CSC self-renewal, invasion, tumorigenicity, the expression of CD133 and of pluripotency-associated genes: KLF4, SOX2, OCT3/4 and NANOG." (PMID 34583655, 2021). "The results showed that expression of WDR12 was strongly increased in tumor cells expressing SOX2." (PMID 34868955, 2021). "Based on accessibility to SOX2, the fraction of the tumor cells represented around 80%." (PMID 34599169, 2021). "Interestingly, decreased expression of SOX2 was noted in tumor samples compared with the respective control tissue samples, while there were no significant changes in the expression of SOX2 after NaBT treatment on Caco-2 cells." (PMID 33471801, 2021). "Based on these evidences, we speculated that PAK2 upregulation might perform its tumor-promoting efficacy through increasing the phosphorylation and nuclear distribution of SOX2 in OC cells." (PMID 34621737, 2021). "Transcriptomic studies and proliferation and marker analyses all indicate that reduction of SOX2 dosage compromises most aspects of tumorigenesis in p27−/− animals, implying an essential role for SOX2 in p27−/− melanotrophs and adjacent SCs for tumor development." (PMID 33574062, 2021). "In contrast, after Sox2 was overexpressed, the cell cycle progressed and promoted tumour growth." (PMID 33986256, 2021). "Interestingly, immunostaining found that, while circFat1 reduced SOX2+ tumor cells, SOX2+ tumor cells were enriched after anti‐PD1 treatment, indicating that SOX2+ tumor cells were intrinsically resistant to PD1 blockade." (PMID 34258151, 2021). "GANT61 treatment significantly decreased BMI1 and SOX2 expression in vivo in tumor xenografts." (PMID 33499351, 2021). "Interestingly, we found a strong association between SOX2 expression and the concentrations of serum ALT, a specific enzyme of the liver, and also of the AFP tumor marker." (PMID 34436030, 2021). "Because deletion of p27 induces up-regulation of SOX2 in SCs, we asked whether the SCs flanking the IL directly give rise to tumor cells or induce tumorigenesis." (PMID 33574062, 2021). "However, previous studies have contradictory results on GBM growth; some studies showed that Sox2 contributed to GBM growth by promoting the cell cycle into the S phase, and knockdown of Sox2 attenuated S phase entry, thus inhibiting tumour growth." (PMID 33762574, 2021). "Of note, by NanoString nCounter assay exploring the expression of 740 genes involved in the four major processes of tumor progression (angiogenesis, extracellular matrix, epithelial–mesenchymal transition, and metastasis), SOX2 gene expression has been recently detected in parathyroid cancers." (PMID 34199594, 2021).
tumor (continued). "However further experimental studies would be required in order to clarify the biological role of PGRMC1 in tumor stemness associated pathway, such as OCT3/SOX2/NANOG/KLF4." (PMID 34746100, 2021). "First, how does elevating SOX2 in different tumor cell types influence tumor growth?" (PMID 32998722, 2020). "This might be attributed to SOX2+ tumor cells that induce a cellular stem cell state in human CRC with low levels of CDX2 expression." (PMID 30517668, 2020). "Gaining insights into the molecular mechanisms by which elevated SOX2 arrests the growth of tumor cells could identify therapeutic targets for the eradication of quiescent tumor-initiating cells, thus helping to address a major unmet need." (PMID 32998722, 2020). "In lung squamous cell carcinoma (LSCC) tumor-spheres, SOX2 activation induced upregulation of Hh acyltransferase (HHAT), a critical component that palmitoylates Hh ligands, and induced autocrine pathway activation to drive growth of LSCC tumor-spheres but not bulk LSCC cells nor LAD tumor-spheres." (PMID 32108165, 2020). "In addition, replacing endogenous OCT4 with OCT4 S236D reduced tumor growth and a population of cells positive for SOX2, one of the undifferentiation markers, in mouse xenograft experiments in vivo." (PMID 32932964, 2020). "In addition, the prognostic implication of SOX2 immunostaining in these tumours need to be addressed." (PMID 33489519, 2020). "In addition, there is evidence that SOX2 is an upstream protein of the Hh signaling pathway, and acts to alter the cell proliferation potential and maintain the stemness of tumor cells." (PMID 31967981, 2020). "Interestingly, our earlier studies with PDAC cells demonstrated that both elevating SOX2 and knocking down SOX2 inhibit tumor growth." (PMID 32998722, 2020). "Thus, we proposed that SOX2 levels in tumor cells are optimized to maximize tumor growth – too little or too much SOX2 reduces tumor growth." (PMID 32998722, 2020). "On the other hand, the knockdown of SOX2 in different cell lines, including gastric, significantly reduces proliferation in vitro and tumor growth SOX2 has also been shown to promote tumor invasion, migration, and metastasis in numerous cancers." (PMID 32093282, 2020). "In these areas, SEL1L+ tumour cells corresponded to Nestin+ and Sox2+ cells." (PMID 31111685, 2020). "Importantly, SOX2 expression significantly correlated with higher tumor grade (p = 0.001), poor differentiation (p = 0.005), and the presence of vascular (p = 0.003) or lymphatic invasion (p = 0.005)." (PMID 32295077, 2020). "SOX2 could activate important gene cascades for all these cancers that may affect a variety of functions, such as tumor proliferation, migration, and drug resistance." (PMID 32130794, 2020). "Finally, our studies provide new and surprising insights into the molecular mechanisms by which SOX2 inhibits the proliferation of tumor cells." (PMID 32998722, 2020). "However, strikingly, a subset of HNSCC patients (33.3%) harbored high expression of NANOG and SOX2 in histologically normal mucosa with comparable levels to the matched tumor." (PMID 32635524, 2020). "This also hints that SOX2 promoter was epigenetically suppressed in differentiated tumor cells." (PMID 30517668, 2020). "In GBM cell population, SOX2, along with POUF3F2, SALL2 and OLIG2, forms a group of core transcription factors that triggers an epigenetic effect in cancer cells leading to a formation of tumor propagating cancer stem-like cells, making SOX2 a good candidate for cancer stem cell marker." (PMID 32092088, 2020). "Collectively, our work and that of others supports the hypothesis that elevated levels of SOX2 limit the proliferation of several types of tumor cells." (PMID 32998722, 2020). "To exclude the tumor cell context effect of SOX2 expression, we also conduct this luciferase reporter assay in 293T cells and found similar crucial role of nt-645–656 for SOX2 expression, suggesting general regulation of SOX2." (PMID 31887658, 2020).
tumor (continued). "Targeting SOX2+ cancer cells could be a strong therapeutic strategy to expunge CSCs and the approach requires bona fide study because SOX2 is also expressed in normal stem cells, and in general, SOX2+ tumor cells remain quiescent." (PMID 30517668, 2020). "In addition, positive nuclear SOX2 expression in >10% of tumor cells was detected in 105 (30%) tumor samples." (PMID 32635524, 2020). "Finally, we examined how elevating SOX2 in the MB cell line ONS76 (i-SOX2-ONS76) affected tumor growth." (PMID 32998722, 2020). "Elevating SOX2 in diverse tumor cell types led to growth inhibition in vitro." (PMID 32998722, 2020). "In addition, we demonstrate in four tumor cell lines, representing three different tumor types, that elevating SOX2 leads to a reversible state of tumor growth arrest." (PMID 32998722, 2020). "In addition, WISP1 disruption by shRNA significantly decreased the GSC population as measured by SOX2 immunofluorescence in tumor xenografts." (PMID 32541784, 2020). "This might explain one possible pathway in which SOX2+ tumor cells could exhibit an enhanced resistance to chemotherapeutics and long-term tumor-propagating capability." (PMID 30517668, 2020). "The results showed that FBX8 could upregulate CK, E-cadherin, Sox-2, Caspase-3, and some other markers related to tumor cell dormancy." (PMID 32796813, 2020). "Western blot detection showed that hsa_circ_0068307 knockdown downregulated c-Myc and the CSC-related proteins, NANOG, OCT-4, and Sox-2 in tumor tissues, which further validated the regulatory role of hsa_circ_0068307/miR-147/c-Myc in in vivo BCa xenograft model." (PMID 32398967, 2020). "In addition to the work from our laboratory, including the studies reported here, there are a growing number of reports that strongly support the conclusion that tumor cells hijack the normal growth inhibitory effects of elevated SOX2 for their own needs." (PMID 32998722, 2020). "Remarkably, tumor growth resumed rapidly when SOX2 returned to endogenous levels." (PMID 32998722, 2020). "For instance, Sox2 is involved in mammosphere formation in vitro and tumor growth in vivo." (PMID 33228022, 2020). "As an alternative method, the use of reporter systems where the expression of a fluorescent protein is driven by the SOX2 and/or OCT4 promoter or by SOX2/OCT4 response elements has proved the tumor-propagating potential of cells expressing pluripotency factors in several tumor models." (PMID 32295077, 2020). "SOX2 staining of the implanted tumor tissues with different treatments supported this finding." (PMID 32194860, 2020). "In both luminal and triple-negative FMCs, a positive association was found between Sox2 expression and tumor size." (PMID 33553286, 2020). "For example, it has been shown that cells displaying low SOX2 expression, such as Panc1 and Patu8988T, also presented stem-like cell properties and were still capable of tumor initiation and metastasis in xenograft even though they presented lower self-renewal capability in sphere-forming assay." (PMID 32457900, 2020). "In support of this hypothesis, it was found that tumor-residing macrophages can induce Sox2 expression in murine breast cancer cells in a STAT3-depending manner and thereby increase CSC activity." (PMID 33228022, 2020). "SOX2 has been characterized as s a marker for stem-like tumor cells in bladder cancer." (PMID 32427884, 2020). "Finally, we demonstrate in six different cell lines, representing four different tumor types, that SOX2 elevation decreases multiple proteins that regulate progression through each phase of the cell cycle." (PMID 32998722, 2020). "However, Sox2 was not only present in those tumor cells that express stem cell markers, but was equally abundant in other tumor cells." (PMID 33228022, 2020). "The result showed that SAHA could reduce the tumor burden and partially reversed SOX2-induce tumor promotion effect." (PMID 33158915, 2020).
tumor (continued). "Interestingly, and in contrast to our findings, several earlier studies reported that stable overexpression of SOX2 increased the proliferation of tumor cells." (PMID 32998722, 2020). "Thus, elevating SOX2 does not appear to increase cell death, which is consistent with the rapid resumption of tumor growth when SOX2 returns to endogenous levels." (PMID 32998722, 2020). "It was argued that reactivation of SOX2 could explain tumor heterogeneity by placing the self-renewal ability and tumor-initiating capacity in any cell along the axis of mammary differentiation." (PMID 32478091, 2020). "It has been suggested that Sox2+ or CD15+ tumor cells act as cancer stem cells." (PMID 33066274, 2020). "To determine whether elevation of SOX2 induces a reversible state of tumor growth arrest in additional tumor types, we tested two PCa lines and one MB line." (PMID 32998722, 2020). "Furthermore, recent studies have shown that quiescent tumor cells express higher levels of SOX2 compared to adjacent proliferating cells." (PMID 32998722, 2020). "The multiple preclinical studies have shown that SOX2 knockdown mediated by siRNAs, shRNAs or miRNAs dramatically suppresses proliferation and invasion of cancer cells in both in vitro cell culture and in vivo xenograft tumor models." (PMID 31748974, 2020). "Interestingly, histologically normal mucosa from various patients (33.3%, 5/15 cases) also exhibited increased expression of NANOG and SOX2, showing comparable mRNA levels in both the tumor sample and the patient-matched normal tissue." (PMID 32635524, 2020). "Thus, the SOX2 “Goldilocks” zone for tumor cell proliferation appears to be highly context dependent." (PMID 32998722, 2020). "Because DNMT1-mediated methylation downregulated FOXO3a expression, we next tested whether pharmacological inhibition of DNMTs could suppress tumorigenesis and tumor growth by regulating FOXO3a/FOXM1/SOX2 signaling." (PMID 31296961, 2020). "In all three tumor types, elevation of SOX2 in vivo quickly halted tumor growth." (PMID 32998722, 2020). "Additionally, elevating SOX2 in vivo in four tumor cell lines, representing three human tumor types, leads to a reversible state of tumor growth arrest." (PMID 32998722, 2020). "Medulloblastoma growth paralleled a developmental stem cell hierarchy driven by quiescent SOX2+ tumor-initiating cells and therapeutic interference with the SOX2+ cells could stop tumor growth." (PMID 30517668, 2020). "Our previous work proved Sox2 as a marker for stem-like tumor cells of BCa in vivo." (PMID 32676121, 2020). "We showed the dual function of Snail in tumor initiation and angiogenesis in vivo and in vitro through activation of Sox2 and VEGF, suggesting Snail may be an ideal target for cancer therapy." (PMID 32541667, 2020). "We have previously shown that SOX2 is a marker of poor patient prognosis in GC, which would be in accordance with the more aggressive behavior of the cells that express SOX2, namely increased proliferation, increased tumor-formation, and increased drug resistance, observed in this study." (PMID 32093282, 2020). "Recent findings showed that METTL3 expression was higher in CRC tissues than in normal tissues and that this feature indicated poor prognosis; upregulation of METTL3 promoted CRC tumor growth by stabilizing SRY-box 2 (SOX2) and cyclin E1 (CCNE1) mRNA in an m6A-dependent manner." (PMID 32429972, 2020). "Regarding core pluripotency factors, enhanced NANOG expression is observed under hypoxic stimulation within BCSCs17, while conditional SRY-box2 (SOX2) deletion in mice significantly represses the formation of skin squamous-cell carcinoma as a result of tumour regression." (PMID 32913192, 2020). "In FMCs, Sox2 expression was restricted to neoplastic cells, and not found in cancer-associated fibroblasts, tumor-infiltrating lymphocytes, endothelial cells, or any other stromal cell." (PMID 33553286, 2020).